LDHA (lactate dehydrogenase A)
Diseases named in the same sentence as LDHA in open-access papers (continued):
Sharing a sentence is not in itself a finding about the gene and the disease.
tumor (continued). "Owing to the essential role of LDHA in glucose metabolism, it has been implicated in tumour maintenance, alteration in tumour microenvironment and promotion of tumour growth and metastasis." (PMID 34128320, 2021). "In recent years, many studies have found that LDHA is involved in lactic acid-associated tumor immune infiltration and immune escape." (PMID 34307169, 2021). "LDHA-related lactic acid accumulation can even directly disrupt T cells and NK cells, causing tumor immune escape." (PMID 34307169, 2021). "Elevated lactate dehydrogenase A (LDHA) is associated with poor outcomes in human cancer patients, and tumor secreted lactate impairs NK cell function in several mouse tumor models." (PMID 33670082, 2021). "Inhibition of LDHA typically results in accelerated oxygen consumption, reduced cell malignant transformation and markedly delayed tumor formation, indicating the underlying role of LDHA in tumor initiation or maintenance." (PMID 34463208, 2021). "Increased expression of LDHA induces hypoxic environments that are associated with tumor metastases, poor overall survival, and radio-resistance in several tumor types, including prostate and bladder cancers." (PMID 33834022, 2021). "As examples, upregulation of LDHA levels in pancreatic and esophageal cancer have been associated with metastasis, tumor stage, tumor recurrence, and patient survival." (PMID 32257942, 2020). "In melanoma, the impaired IFNγ expression in tumor-infiltrating T cells and NK cells, along with LDHA activity associated lactate production, promotes tumor growth by exerting an immunosuppressive phenomena." (PMID 31546918, 2019). "Transcriptional induction of LDHA can also be caused by hypoxia, which is often a consequence of lower oxygen delivery vs. consumption mismatch, occurring when tumor cell proliferation outstrips neoangiogenesis during tumor growth." (PMID 31035592, 2019). "Group 3 is the most metastatic subgroup of MB and carries the poorest prognosis; these features are also commonly associated with LDHA and lactate concentrations in other tumours." (PMID 29601482, 2018). "Lactate dehydrogenase A (LDHA) is a key enzyme in the aerobic glycolysis pathway, an abnormal metabolic pathway commonly observed in cancers, associated with tumour progression and metastasis." (PMID 29601482, 2018). "Some previous studies have shown that loss of LDHA function by dichloroacetate (DCA) results in dramatically diminished cellular transformation or xenograft tumor growth in breast cancer." (PMID 29629339, 2018). "Fantin et al4 found that under normoxic conditions, the proliferation rate of the cells decreased after downregulating LDHA, and under hypoxic conditions (0.5% oxygen), the growth of tumor cells with LDHA deficiency was also seriously impaired." (PMID 30403008, 2018). "This is clinically relevant because multiple prior tissue studies have reported the association between LDHA-mediated lactate production and tumor aggressiveness in RCCs." (PMID 30189677, 2018). "High rates of glycolysis in tumors exert inhibitory effects on tumor-infiltrating NK cells also via cancer-associated lactate dehydrogenase-A (LDHA)." (PMID 30467503, 2018). "As shown in representative figures, JMJD2A and LDHA expression were positively associated with advanced tumor stages (P < 0.05)." (PMID 28693517, 2017). "LDHA overexpression is also associated with many other poor prognostic factors, including tumor hypoxia 111, angiogenesis 59, proliferation and glucose uptake 41, as well as resistance to chemotherapy 66 and radiotherapy." (PMID 26269128, 2016). "LDHA is associated with tumor initiation, maintenance, progression and poor prognosis in many tumors." (PMID 26269128, 2016). "The increased expression of GLUT1, HK1, PKM2, and LDHA with higher tumor risk grades indicates important roles for these proteins in GIST tumorigenesis and suggests their usefulness in the preoperative prediction of malignant potential." (PMID 26509967, 2015).
tumor (continued). "Most GISTs evaluated in this study showed significant overexpression of the glycolytic enzymes PKM2 and LDHA, with the degree of overexpression increasing with higher tumor risk grade." (PMID 26509967, 2015). "LDHA expression is also elevated in many types of cancers and is linked to tumor growth, maintenance, and invasion." (PMID 26509967, 2015). "LDHA, which executes the final step of aerobic lactate production, is elevated in many human cancers and has been linked to tumor growth, maintenance, and invasion." (PMID 26342198, 2015). "The lactate dehydrogenase A (LDHA) is an enzyme which is encoded by the LDHA gene, located on the short p arm of chromosome 11 (11p15.4), plays a critical branch point in metabolism of tumor cells." (PMID 26062441, 2015). "Inhibition of LDHA reduced cell malignant transformation and remarkably delayed tumor formation, indicating that the underlying role of LDHA in tumor initiation or maintenance." (PMID 25983002, 2015). "Results of qRT-PCR showed a gradual increase in PKM2 and LDHA expression with higher tumor risk grade." (PMID 26509967, 2015). "Although exact mechanism causing SIRT3-mediated LDHA regulation needs to be further investigated, these results demonstrate that LDHA controlled glycolysis pathway that accelerates tumor bioenergetics can be affected by SIRT3 expression levels." (PMID 26121691, 2015). "As the tumorigenicity of the LDHA-deficient cells was severely diminished, LDHA plays a key role in tumor maintenance." (PMID 24885701, 2014). "There was a statistically significant association between the LDHA levels of expression and tumor size; with larger tumors showing significantly higher proportion of LDHA expression (p < 0.001)." (PMID 24885701, 2014). "There was also a stepwise increase in LDHA protein expression that is positively associated with tumor grade (p < 0.001)." (PMID 24885701, 2014). "Previous studies showed an association between up-regulation of LDHA and increased proliferation of tumor cells, particularly those with high malignant potential, and tumors that are poorly differentiated." (PMID 24885701, 2014). "We also found that LDHA level of expression in primary RCC is directly proportional with the tumor size and is associated with significant decrease of both disease free survival and overall survival." (PMID 24885701, 2014). "In addition, LDHA protein expression in tumor tissues was found to be associated with several clinicopathological parameters related to cancer dissemination, including cancer stage, lymphatic invasion, and metastasis to the liver or lungs." (PMID 41368023, 2025). "The lactate-to-pyruvate ratio (Lac/Pyr) correlates strongly with HIF1α expression, linking metabolic activity to hypoxia and tumor volume, while also showing associations with lactate dehydrogenase A (LDHA) and monocarboxylate transporter 1 (SLC16A1/MCT1) expressions." (PMID 41515572, 2025). "Clinical validation confirmed elevated LDHA expression in FH-deficient RCC tumor tissues, which may correlate with immunosuppressive microenvironments and resistance to ICIs." (PMID 41112295, 2025). "Studies indicate that CRCs with high glucose metabolism often exhibit elevated standardized uptake values on PET scans, with concurrent upregulation of hexokinase 2 and lactate dehydrogenase A, which are closely associated with rapid tumor progression and poor prognosis." (PMID 41415548, 2025). "In addition, LDHA activity is associated with malignant proliferation and invasion of tumors and is a potential drug target for tumor treatment." (PMID 40584617, 2025). "LDHA overexpression markedly rescued the reduced tumor volume caused by circSMPD4 knockout." (PMID 40940312, 2025). "Notably, these effects were associated with a marked reduction in LDHA expression, supporting the notion that metabolic inhibition contributes to tumor regression." (PMID 40861817, 2025). "We revealed the association between LDHA expression and tumor metastasis." (PMID 38709280, 2024).
tumor (continued). "Notably, lactate dehydrogenase A (LDHA), a pivotal enzyme in the final phase of this metabolic shift, is prevalent in multiple cancer cells and is intimately linked to tumor dimensions and clinical outcomes." (PMID 39850812, 2024). "This implies that targeted disruption of LDHA and its associated signaling pathways may provide a pathway to inhibit tumor progression." (PMID 38709280, 2024). "Elevated levels of LDHA are a hallmark of many tumours, most of which are highly glycolytic." (PMID 39417674, 2024). "Both LDHA and LDHB were associated with tumor immune infiltrates in ccRCC patients, which suggested LDHA/LDHB could be implicated in the tumorigenesis of ccRCC and might be potential therapeutic targets for patients with ccRCC." (PMID 37547725, 2023). "Additionally, glycolytic enzyme lactate dehydrogenase A (LDHA), which converts pyruvate to lactate, is associated with tumor initiation, development, and metastasis." (PMID 37568652, 2023). "Moreover, sodium lactate attenuated the suppression of tumor cell proliferation and migration induced by LDHA/B deficiency." (PMID 37684641, 2023). "The inactivation of lactate dehydrogenase A (LDHA) because of desuccinylation on Lys118 is hypothesized to be the cause of the tumor suppressor function of SIRT5." (PMID 36980194, 2023). "Then, retrospective IHC analysis revealed that the expression levels of LDHA and LDHB were significantly associated with tumor grade, stage, size, and OS, which indicated that enhanced LDHA and decreased LDHB were positively correlated with ccRCC aggressiveness." (PMID 37547725, 2023). "Elevated LDHA expression is also associated with poor outcome in tumor patients." (PMID 35359405, 2022). "Therefore, similar to the genetic inhibition of LDHA, oxamate treatment also results in tumor suppression due to the loss of LDHA activity." (PMID 35982980, 2022). "Research shows that LDHA overexpression is associated with malignant behavior of tumor cells." (PMID 35535311, 2022). "Moreover, LDHA-associated lactic acid accumulation in ABC DLBCL is critical for tumor aggressive progression." (PMID 35359405, 2022). "Moreover, our study provided in vivo evidence that PlGF silencing caused down-regulation of C-myc and LDHA by examining tumor xenografts harvested from mice and in vitro evidence that PlGF overexpression resulted in up-regulation of C-myc and LDHA." (PMID 33407494, 2021). "Western blot analysis of PlGF, β-catenin, C-myc and LDHA in tumor tissues revealed that depletion of PlGF caused significant reductions of protein levels of C-myc, β-catenin, and LDHA in shPlGF xenografts, which were in accordance with the results in H358 and H1975 cells." (PMID 33407494, 2021). "Moreover, it was shown that the LDHA-dependent glycolytic tumor cells are increasingly susceptible to FX11 treatment, when compared with other cells dependent on mitochondrial oxidative phosphorylation for energy generation." (PMID 32034005, 2020). "Furthermore, elevated serum LDHA levels are associated with tumor burden as well as poor clinical outcome to PD-1 and CTLA-4 immune checkpoint blockade therapy." (PMID 31932876, 2020). "Perhaps the advances in tumor immunometabolism could be useful to infer plausible mechanism(s) associated with LDHA inhibition in the context of TB pathogenesis." (PMID 32034005, 2020). "HIF 1-α is associated with metabolic regulation, specifically with tumor lactagenesis, because of the induction of the expression of LDHA, MCT4 and the membrane-bound carbonic anhydrase IX (CAIX), and in this way regulates the tumor acid environment and tumor progression." (PMID 31737570, 2019). "The molecular mechanism underlying the LDHA inhibition and anti-tumor activity was investigated." (PMID 30850682, 2019). "Enhanced expression of LDHA, which is needed for maintaining glycolysis and other metabolic activities, has been associated with the evolution of aggressive and metastatic cancers in a variety of tumor types, including cervical cancer." (PMID 30356100, 2018).
tumor (continued). "In summary, we have demonstrated the feasibility of HP 13C pyruvate MRI to noninvasively interrogate tumor lactate production and compartmentalization in a murine orthotopic model of human RCCs, and to inform on tumor LDHA and MCT4 expression which are implicated in tumor aggressiveness." (PMID 30189677, 2018). "LDHA is elevated in many types of cancers and has been linked to tumor growth, maintenance, and invasion; therefore, its inhibition may restrict the energy supply in tumors and thereby reduce the metastatic and invasive potential of cancer cells." (PMID 28970582, 2017). "This indicated that TOP1MT deficiency promoted the invasion and metastasis of tumor cells mainly through the Warburg effect and that LDHA may have played an important role in this process." (PMID 28874393, 2017). "Many examples of pharmacological inhibition of members of the upstream (2-DG) or downstream (LDHA) glycolytic pathway were shown to be effective in blocking tumor growth but the associated toxicity and low benefit of this approach prevented their development in the clinic." (PMID 29152106, 2017). "Furthermore, a number of studies have shown that LDHA levels are associated with tumor sensitivity and resistance to therapeutic agents." (PMID 24884974, 2014). "The significance and the regulation of LDHB expression in cancer development remains unclear, but different tumor phenotypes may originate from the alteration of LDHA and LDHB caused by mutation, chromosomal deletion/duplication, and increase of copy number." (PMID 25372838, 2014). "Furthermore, it was demonstrated that LDHA is involved in tumour genecity and its reduction causes bioenergetic and oxidative stress leading to cell death." (PMID 21124955, 2010). "Interestingly, in the present study, LDHA encoding lactate dehydrogenase A was downregulated in LGG tumor tissues, which may cause less lactate accumulation, leading to reduced growth and invasion of LGG, despite the MCT1 (SLC16A1) upregulation." (PMID 40782248, 2025). "Thus, LDHA may be another target that is related to lncRNAs and mediated tumor pathogenesis and development, but the underlying mechanism needs to be urgently investigated." (PMID 36072431, 2022). "Simultaneously inhibiting LDHA via sodium oxamate and respiratory complex I via metformin depletes the cellular ATP pool, causing cancer cells to undergo metabolic catastrophe, leading to tumor cell growth arrest and cell death, leading to significant decreases in tumor size." (PMID 33718271, 2021). "In addition, the expression level of LDHA was closely associated with tumor size, TNM stage and prognosis in PC patients, indicating that LDHA may be a potential prognostic marker and therapeutic target of PC." (PMID 28193910, 2017). "Immunofluorescence staining confirmed the downregulation of both AKR1B10 and LDHA protein levels in the combination group within the LR PDX tumours." (PMID 41454479, 2026). "LDHA knockdown suppressed tumor growth, glycolysis, mitochondrial respiration, and induced apoptosis." (PMID 42039141, 2026). "LDHA is an important rate-limiting enzyme in the glycolytic pathway, playing a crucial role in promoting tumor malignancy by regulating tumor energy metabolism." (PMID 41507134, 2026). "While LDHA's role in tumor metabolism is well‐documented, LDHB functions appear more context‐complex." (PMID 40818043, 2026). "To validate these findings, we examined 27 paired clinical ccRCC samples, confirming significantly higher YBX1 and LDHA protein expression in tumor tissues versus adjacent normal tissues by western blot, with positive correlation between the two proteins." (PMID 41507134, 2026). "Accumulating evidence demonstrates that LDHA is essential for primary tumor growth and critically involved in circulating tumor cell (CTC) survival, anoikis resistance, and metastatic spread." (PMID 41977425, 2026).
tumor (continued). "Recent studies have repositioned the clinically approved antiepileptic drug stiripentol (STP) as a potent lactate dehydrogenase A inhibitor that effectively disrupts tumor metabolic reprogramming, thereby reinstating tumor control." (PMID 41764441, 2026). "Crucially, combined targeting of RACK1 with c-Src or LDHA inhibition yielded synergistic anti-tumor effects in vivo, significantly surpassing monotherapies." (PMID 42215440, 2026). "The results demonstrated a higher level of LDHA lactylation in tumor tissues compared to adjacent normal tissues." (PMID 41190808, 2026). "LDHA is a key enzyme in the glycolytic pathway and a critical driver of the Warburg effect in tumor cells." (PMID 41190808, 2026). "Correspondingly, Nat10 depletion promoted the lactate dehydrogenase A (LDHA) release in OVA-WT tumor cells cocultured with OT1 CD8+ T cells." (PMID 41542770, 2026). "ADX markedly reduced intratumoral DHT and downregulated glycolytic genes (HK2, PFK2, and LDHA) and secretory proteins expressed by the tumor, including stanniocalcin 2, potentially mediating paracrine effects in the sclerotic bone response." (PMID 42149634, 2026). "Collectively, these data establish LDHA as a core effector for circSMPD4's biological functions, indispensable for circSMPD4‐promoted tumor immune evasion and tumor progression." (PMID 40940312, 2025). "The results showed an increased expression of ADAMTS5, CDCA8, and LDHA in tumor tissues, suggesting their significant regulatory roles in HCC." (PMID 40647517, 2025). "LDHA expression in PTC tissues has been found to positively correlate with tumor size, lymph node metastasis, and TNM stage in numerous studies." (PMID 40917751, 2025). "Tumor cells enhance lactate dehydrogenase A (LDH-A) activity to convert pyruvate into lactate, which is then exported out of the cell via monocarboxylate transporter 4 (MCT4), further acidifying the TME." (PMID 40370433, 2025). "In this model, tumor LDHA was shown to upregulate CCL2/CCL7 via the ERK → YAP1/STAT3 pathway, thereby recruiting macrophages." (PMID 41463052, 2025). "To further explore the connections between LDHA expression and CD8+ T cell-mediated anti-tumor effects, we constructed LDHA-Sh1 plasmids to knockdown LDHA." (PMID 39990209, 2025). "In cancer treatment, these drugs suppress LDHA expression, thereby inhibiting cell proliferation, migration and tumour formation." (PMID 41190507, 2025). "In NSCLC, upregulation of NCAPD3 promotes tumor growth via the MEK/ERK/LDHA signaling axis, with histone lactylation enhancing NCAPD3 expression and amplifying glycolysis and malignant phenotypes." (PMID 41373440, 2025). "As a key rate-limiting enzyme in the aerobic glycolysis of tumor cells, the inhibition of LDHA activity has emerged as a novel target in cancer therapy." (PMID 41561760, 2025). "Acetylation at lysine 118, catalyzed by lysine acetyltransferases 7 (KAT7), enhances both LDHA enzymatic function and protein stability, ultimately promoting tumor proliferation." (PMID 41152975, 2025). "LDHA expression intensity correlates closely with tumor histological grade and myometrial invasion depth." (PMID 41561760, 2025). "Inhibiting LDHA, for example, reduces lactate accumulation and increases tumor cell sensitivity to radiation." (PMID 41441035, 2025). "Flow cytometry analysis of NK cell cytotoxicity assays revealed that LDHA knockout significantly reduced tumor cell resistance to NK‐cell‐mediated cytotoxicity, while LDHA overexpression yielded opposite results." (PMID 40940312, 2025). "Experimental studies indicate that inhibiting LDHA effectively suppresses tumor cell growth capacity." (PMID 41561760, 2025). "Single-cell metabolomics further revealed that M2-TAM subsets preferentially uptake lactate via upregulated monocarboxylate transporter 1 (MCT1), relying on lactate dehydrogenase A (LDHA) to sustain their pro-tumor phenotype." (PMID 40703527, 2025).